CD24 (CD24 molecule)
Diseases named in the same sentence as CD24 in open-access papers (continued):
Sharing a sentence is not in itself a finding about the gene and the disease.
infection (continued). "The robust differences observed in Zika virus permissiveness, as shown in the bright field images in S5 Fig suggest a dramatic change in the phenotype of CD24-expressing cells compared to their control cells after infection with Zika virus." (PMID 30044847, 2018). "All cells positive for infection showed >86% cell surface expression of the marker protein (CD24, SSEA4, HLA-1 and CD9) by flow cytometry." (PMID 22536330, 2012). "Antibodies recognizing SSEA4 and CD24 mediated the selective infection of the iPS cells over the parental human fibroblasts, allowing for rapid expansion of these cells by puromycin selection." (PMID 22536330, 2012). "Infection of CD24(hi) cells demonstrates that neuronal precursor cells are highly susceptible to infection with MCMV." (PMID 21249143, 2011). "After sorting of CD24− and CD24+ populations, CD24+ cells were seeded onto 96-well plates under limiting dilution cloning conditions in order to isolate single cells (day 30 post-infection)." (PMID 18682804, 2008). "As Ras and TGFβ are known to cooperate in EMT induction, we then assumed that, in presence of TGFβ, the length of time needed to generate CD24− cells from CD24+ HMLE cells following infection with Ras should be shortened." (PMID 18682804, 2008). "Interestingly, whereas the CD24:CD49f marker profile of MS dissociated on day 12 post infection was not significantly changed upon loss of GSK-3 across replicate experiments, a prominent CD24hi:CD49flo/− population was observed upon stabilization of β-catenin." (PMID 25195860, 2015). "The differences between the different vector transduced cell populations could not be attributed to differences in infection levels since flow cytometry using PE-conjugated antibody to mouse CD24 (heat stable antigen) present in the challenge virus showed comparable levels of infection." (PMID 18534033, 2008). "We found that IAV infection led to upregulation of MHCII either by the proportion of cells that were MHCII+ or increased expression on upper (ciliated, club), progenitor (CD24+, Sca1+), and lower airway (ATII) epithelial cells at day 10 post-infection." (PMID 40750594, 2025). "We also found small but significant increases of MHCII on CD24+ progenitor and ATII populations at day 30 post-infection compared to levels in cells from naive mice." (PMID 40750594, 2025). "A specific CD24+ T-cell is responsible for CMV immunity and is important for both adult infection and fetal involvement." (PMID 36292118, 2022). "Untreated CD24-low and -high cells showed ~20% and 50% GFP+ cells, respectively, demonstrating an inherent difference in their permissivity to PIV5-P/V infection." (PMID 36016357, 2022). "The observed gradual decrease in the number of ciliated cells and increase in CD24+Epcam+ and CD133+ cells suggest a sustained shift in the regulation of epithelial renewal during infection." (PMID 30886143, 2019). "At 72 hours post infection, the virus titer in CD44+CD24+ESA+ cells was approximately fifteen times higher at MOI 0.01, and ten times higher at MOI 10 in comparison to CD44+CD24-ESA+ cells." (PMID 22901246, 2012). "The surface expression of LFA-1, LFA-3, CD44, CD24, and in particular of CD62L molecules, was induced after VV and VV:ΔHA infection of HeLa cells (unpublished results)." (PMID 21901096, 2011). "Importantly, these CD14+ PMNs expressed APP antigens and exhibited the characteristics of apoptotic cells, as they highly expressed CD24 and CD36, markers of apoptotic PMNs, indicating that these cells play a key role in the recovery stages of infection." (PMID 37705063, 2023). "As controls, CD24-high cells were either left untreated (black bars, negative control) or were treated with exogenous IFN-I (black bar, positive control) before their infection with VSV-EGFP." (PMID 36016357, 2022).
infection (continued). "In the HIV-HSA genome, an internal ribosome entry site (IRES) was constructed before the Tat gene to keep the infection active, and the cellular membrane-bound mouse HSA, the murine CD24 (60 amino acids), is expressed along with early viral genes upon productive infection." (PMID 34233649, 2021). "However, PRH overexpression did not alter expression of CD44 and CD24 marker proteins in cells prior to mammosphere formation at 48 h post-infection as measured using flow cytometry." (PMID 28604763, 2017). "IFN-α-supported plasmablast and CD24+CD38hi Breg cell generation might also depend on the integration of other inflammatory signals, in particular the levels of CD40L expression, or the profile of cytokines produced over the course of the infection by contiguous or interacting cells." (PMID 26968426, 2016). "By contrast, the frequency of CD38++CD24++ Breg cells and of CD38++CD24- plasmablasts appeared to be unaffected by infection (not shown)." (PMID 39136010, 2024). "We measured the expression of mouse CD24 and GFP in the infected macrophages treated with or without imiquimod on day 3 post-infection." (PMID 34356516, 2021). "CD44 expression was up-regulated in dose-dependent fashion, whereas CD24 was not significantly changed, revealing a CD44+/CD24−/low phenotype following infection." (PMID 33233485, 2020). "Colonic CD11c+ CD64+ CD24+ macrophages, but neither CD103+ CD11b− DC nor CD103− CD11b+ DC responded to the infection with il23a induction." (PMID 25761673, 2015). "The trafficking of TLR9 in JIMT-1 CD44-/CD24- non-CIC population showed a similar pattern as ArLa non-CIC: The receptor was found in the ER and at low levels in endosomes in non-infected cells and upon infection TLR9 was upregulated and trafficked from the ER to the endosomes." (PMID 21079774, 2010).
adenocarcinoma (13 papers, 2003 to 2022). A common cancer characterized by the presence of malignant glandular cells. "Our previous mass spectrometry-based proteomics study revealed that annexin A10 (ANXA10) was uniquely overexpressed in pancreatic CD24+ adenocarcinoma cells that were dissected from clinical PDAC tissues but was absent in CD24- adjacent normal cells." (PMID 28369074, 2017). "Immunohistochemical analysis of human colonic specimens showed differential staining patterns for CD24 in normal tissue, colonic adenomas, and adenocarcinomas." (PMID 26078485, 2015). "Class B cell lines (CLB) are adenocarcinomas exhibiting a pure epithelial morphology and the EpCAM+CD24+CD44+CD133+ phenotype." (PMID 26158412, 2015). "In our TNBC model, we found up-regulation of Pou5F1 (Oct-3/4), Kit, Cd24 and Itga6 (Cd49f) in epithelial-like adenocarcinoma areas of primary tumors, while Klf4, Sox2, Cripto-1 were expressed in the mesenchymal/EMT-like regions." (PMID 26059540, 2015). "CD24 staining was prominent and intense in the epithelial layers surrounding the fibrillar deposits found in the squamous metaplasia, while staining was weaker in adenocarcinomas." (PMID 26978528, 2016). "CD24 expression was significantly higher in adenocarcinomas (Fishers exact test, P=0.001)." (PMID 12610508, 2003). "A high level of CD24 expression was observed in 45% of the cases, preferentially adenocarcinomas." (PMID 12610508, 2003). "Therefore, the evaluation of the coexpression of ANXA10 and CD24 could help understand the potential role of ANXA10 during the progression of pancreatic precursor lesions to adenocarcinoma." (PMID 28369074, 2017). "The heatmap shows the inter-cell-line heterogeneity of the adenocarcinoma cells while the following markers showed the highest expression in the panel: EGFR and CD24 in the case of A549; CD326 and CD274 for H1975; and CD326 and EGFR for H1650." (PMID 35008313, 2021). "Of these, survival was best predicted by CDK1 (p<1E-16), CD24 (p<1E-16) and CADM1 (p = 7E-12) in adenocarcinomas and by CCNE1 (p = 2.3E-09) and VEGF (p = 3.3E-10) in all NSCLC patients." (PMID 24367507, 2013). "Interestingly, in our previous proteomics study, ANXA10 was found uniquely overexpressed in pancreatic CD24+ adenocarcinoma cells but was absent in CD24- adjacent normal cells." (PMID 28369074, 2017).
hematological malignancies (5 papers, 2021 to 2025). "Combined with peripheral blood CD11b expression, surface CD24 has also been evaluated as a potential screening tool for the detection of hematologic malignancies." (PMID 36013184, 2022). "Following the successful implementation of CAR T cell immunotherapy in hematologic malignancies, some preclinical studies have employed engineered immune cells to target CD24 in solid tumors." (PMID 36013184, 2022). "Our primary aim was to assess the sensitivity and specificity of the CD24/CD11b-based blood test for the detection of hematological malignancies." (PMID 34442367, 2021). "In conclusion, our findings indicate the feasibility of a CD24/CD11b-based blood test as a screening test of hematological malignancies." (PMID 34442367, 2021). "Our sensitive analysis demonstrated that this statistically significant difference was not affected by age or gender, and therefore indicate the rationale for assessing CD24 as a possible biomarker for hematological malignancies." (PMID 34442367, 2021). "In our study, an increase in the peripheral blood levels of CD24/CD11b was found among subjects with hematologic malignancies compared to healthy subjects." (PMID 34442367, 2021). "CD24 is a mucin-like cell surface molecule and P-selectin ligand, which plays a significant role in the maturation of B-lymphocytes and was found to be overexpressed in a number of hematological malignancies." (PMID 34442367, 2021). "Our primary aim was to explore whether CD24/CD11b may serve as a biomarker for the early detection of hematological malignancies." (PMID 34442367, 2021). "Therefore, CD24 might play a significant role in certain hematological malignancies, such as MCL and FL, in which the well-known immune checkpoint CD47 may be less relevant." (PMID 35625912, 2022). "In this regard, the overexpression of CD24 has been documented in several malignancies, including breast, lung, colorectal, hepatocellular, pancreatic, ovarian, urothelial, prostate, and head and neck cancer, as well as in primary central nervous system (CNS) tumors and hematologic malignancies." (PMID 36013184, 2022).
metabolic disorders (5 papers, 2023 to 2025). "Among all genes tested, only Siglece mutation phenocopied that of CD24, suggesting that Siglec E is the functional receptor for CD24 in protection against metabolic disorders." (PMID 37228622, 2023). "They finally found that Siglec-E signaling is required for CD24-mediated protection against metabolic disorder and CD24-Siglec-E axis represses metaflammation to ameliorate metabolic disorder." (PMID 38313430, 2023). "The CD24/Siglec-E axis, which serves as an innate immunological checkpoint against metaflammation and metabolic disorders, is a potential therapeutic target for metabolic diseases." (PMID 37846296, 2023). "The data demonstrated a critical role for CD24 in suppressing metabolic disorders." (PMID 37228622, 2023).
benign tumor (2 papers, 2016 to 2021). "In conclusion, a significant increase in the levels of CD24/CD11b was found among subjects with benign tumors as compared to healthy subjects." (PMID 34575716, 2021). "CD24/CD11b expression was analyzed in 1640 participants (23.4 ± 9.7), of which 297 had benign tumors." (PMID 34575716, 2021). "In our study, we found elevated levels of CD24 in participants with benign tumors compared to the CD24 levels of healthy subjects." (PMID 34575716, 2021). "In the present investigation, significantly high percentage of CD19+ CD24+ CD38+ Bregs was seen in the PMBCs of IBCa patients compared with that in benign tumor patients or healthy individuals." (PMID 27762298, 2016). "We confirmed that PD-L1 was higher on CD19+CD24+CD38+ Bregs in IBCa patients compared with patients with benign tumor or healthy individuals." (PMID 27762298, 2016). "In addition, there was a significant difference between the expression of CD24/CD11b levels in participants with benign tumors as compared to healthy subjects." (PMID 34575716, 2021).
cardiovascular disease (2 papers, 2021 to 2025). "We would suggest that exploring the role of CD24 in cardiovascular disease processes may lead to targeted drug development in our research field as well." (PMID 33915986, 2021). "We hypothesize that CD24 is a promising focus of research in the understanding of cardiovascular disease processes and the development of novel biological therapies." (PMID 33915986, 2021).
head and neck tumor (2 papers, 2016 to 2023). "We also found a positive correlation between CD24 expression in head and neck tumor samples and unfavorable cisplatin treatment response retrospectively in a small cohort." (PMID 27276062, 2016).
hematologic cancers (2 papers, 2021 to 2023). "Different solid tumors and hematologic cancers have been shown to overexpress CD24 with an anti-phagocytic signal." (PMID 37846296, 2023). "A significant increase in the levels of CD24/CD11b levels was found among patients with hematological cancers, as compared to healthy subjects." (PMID 34442367, 2021). "Our specific objectives were to assess the sensitivity and specificity of the CD24/CD11b blood test for the early detection of hematologic cancers." (PMID 34442367, 2021). "CD24/CD11b expression in 488 eligible participants was analyzed, and 122 of them were patients with a positive hematological cancer diagnosis." (PMID 34442367, 2021). "A significant difference between the expression of CD24/CD11b levels in the PBLs of hematological cancer patients and healthy subjects is presented." (PMID 34442367, 2021). "Sensitivity and specificity are encouraging for the feasibility of the CD24/CD11b blood test for further development and validation as a hematologic cancer screening test and as an early marker for these diseases." (PMID 34442367, 2021).
colon polyps (1 paper, 2024). "In our study, we found that RuminococcaceaeUCG002 is a risk factor for colon polyps, with its mechanism of action potentially related to the expression of CD24 on IgD-CD38- B cell subsets." (PMID 39346904, 2024). "Increased abundance of RuminococcaceaeUCG002 can cause increased levels of CD24 on IgD- CD38- B cells, which in turn leads to an increased risk of colon polyps." (PMID 39346904, 2024).
gastrointestinal tumors (1 paper, 2015). "CD24 has an important oncogenic role in gastrointestinal tumors." (PMID 26394139, 2015).
inflammation (1 paper, 2024). Aberrant reaction of the microcirculation characterized by movement of fluid and leukocytes from the blood into extravascular tissues. "This study suggests that CD24-Fc treatment could represent a promising new therapeutic strategy for managing chronic systemic inflammation and associated diseases in PWH." (PMID 39763958, 2024).
neurodegenerative disease (1 paper, 2021). A disorder of the central nervous system characterized by gradual and progressive loss of neural tissue and neurologic function. "The involvement of CD24 in cognitive performance and neurogenesis might suggest that CD24 plays a role in neurodegeneration, which may make this model useful in examining neurodegenerative diseases, such as AD." (PMID 33562144, 2021). "Hence, a potential new therapy that can halt, revert, or even prevent AD and other neurodegenerative diseases could be based on the downregulation of CD24, for example, by the administration of antibodies targeting CD24." (PMID 33562144, 2021).
urological diseases (1 paper, 2025). "CD24, TOP2A, IQGAP3, UBE2C, and CRH mRNA levels were also significantly higher in patients with NMIBC than in those with hematuria, which may indicate that they could be used as discriminative biomarkers for BCa detection compared to urological diseases." (PMID 40282460, 2025).
CD24 also shares sentences with these, for which no sentence is quoted: rheumatoid arthritis (10 papers); breast (7); allergic asthma (3); chronic periodontitis (3); myocardial infarction (3); autoimmune thyroiditis (2); bacterial infection (2); benign breast disease (2); blood cancers (2); chondrosarcoma (2); cutaneous melanoma (2); ductal carcinoma in situ (2); fibrosis (2); giant cell arteritis (2); immune deficiency- (2); immune disorders (2); inflammatory breast carcinoma (2); kidney disease (2); meningioma (2); myelodysplastic syndrome (2); nervous system disease (2); non-Hodgkin lymphoma (2); ovarian serous adenocarcinoma (2); prostate (2); pulmonary fibrosis (2); alcoholic fatty liver disease (1); allergic rhinitis (1); and neck cancer (1); ankylosing spondylitis (1); aplastic anemia (1).
A further 96 diseases each share a sentence with CD24 in 1 paper.